CD44 (CD44 molecule (IN blood group))
Diseases named in the same sentence as CD44 in open-access papers (continued):
Sharing a sentence is not in itself a finding about the gene and the disease.
ovarian carcinoma (continued). "In preclinical models of ovarian cancer, CD44-expressing cancer stem cells are more resistant to platinum salts and to paclitaxel than CD44-negative cells." (PMID 30551640, 2018). "Purified populations of OCSCs CD44+/MyD88+ cells are able in vitro and in vivo to differentiate into CD44+/MyD88− mature epithelial ovarian cancer cells." (PMID 29389895, 2018). "The low expression of miR-199a into ovarian cancer stem cells helps to understand why CD44 expression is elevate in these cells." (PMID 29389895, 2018). "Altered expression of several CAMs, such as mucins, integrins, CD44, L1CAM, cadherin, claudins, EpCAM, ALCAM and METCAM/MUC18, is linked to the malignant progression of ovarian carcinoma." (PMID 30274262, 2018). "In contrast to CD133, the level of expression of CD44+/CD24− cells in ovarian cancers seems to have a prognostic value." (PMID 29389895, 2018). "Next, we examined the expression pattern of other growth factor receptors (c-MET and IGF-1R) and one of the putative ovarian cancer stem cell markers, CD44, in tumour specimens from these patients." (PMID 29731973, 2018). "It is important to note that More and Alvero reported a heterogeneity of ovarian cancer tissue for CD44 expression." (PMID 29389895, 2018). "Higher levels of CD44 have been observed to play a major role in deregulated-splicing mediated ovarian cancer progression." (PMID 29914196, 2018). "At cut-off value of above 5% of tumour cells with positive immunostaining, 48% of the ovarian cancer cases were CD44 positive." (PMID 29731973, 2018). "The bispecific CD44-EpCAM aptamer was significantly more effective than either single CD44 or EpCAM aptamer for inhibiting the cells growth or inducing apoptosis in ovarian cancer cells both in vitro and in vivo studies." (PMID 29747682, 2018). "Of note, the lower molecular weight oligomers of HA had better drug delivery effect by targeting CD44 overexpressing ovarian cancer cells." (PMID 29747682, 2018). "In the case of miR122A2, a study published in 2010 showed that it forms a unique cluster with miR214 in epithelial ovarian cancer cells (Type II/CD44-) that was responsible for the regulation of the pro-inflammatory NF-kB pathway and the AKT survival pathway." (PMID 29464034, 2018). "The expression of CD44 correlates with tumor initiation, growth, development of drug resistance, and metastases in ovarian cancer." (PMID 30301218, 2018). "We show that STON2 negatively modulates the stem-like properties of ovarian cancer cells, which are characterized by sphere formation, a CD44+CD24− ratio, and by CSC- and epithelial mesenchymal transition (EMT)-related markers." (PMID 30518424, 2018). "It has been postulated that while human ovarian cancer stem cells are CD24+CD44+, human embryonal carcinoma stem cells are CD133+SSEA4+." (PMID 30375490, 2018). "Owing to these properties, CD44 serves as effective tool for pathological diagnosis and prognostic prediction of ovarian cancer in a clinical setup." (PMID 30121075, 2018). "In ovarian cancer xenografts, cancer cells co-expressing EpCAM and CD44 or CD24 had stemness properties with resistance to doxorubicin and cisplatin." (PMID 30551640, 2018). "ALDH+, CD133+, CD44+/CD117+ presenting differential response to chemotherapeutic drug were recently isolated from ovarian cancer cell line SKOV3." (PMID 30121075, 2018). "Upregulated VCAN promoted the motility and invasion of ovarian cancer cells by upregulating expression of CD44 and receptor of hyaluronic acid-mediated motility (RHAMM)." (PMID 29747682, 2018). "It has been shown to inhibit the migration of CD44-expressing cells of ovarian cancer cell lines as well as metastasis by B16-F10 cells, a murine melanoma cell line." (PMID 28264026, 2017). "An extensive literature search in the PubMed, EMBASE, and Wanfang databases (up to June 1, 2016) was conducted to identify studies that assessed the clinical or prognostic significance of CD44 expression in ovarian cancer." (PMID 28070170, 2017).
ovarian carcinoma (continued). "Previous studies suggested CD133 and CD44 as the most frequent markers for isolation of prostate and ovarian cancer cells." (PMID 29213108, 2017). "Whereas in renal cell carcinoma a high expression level of CD44 is related to poor outcome, in ovarian cancer overexpression of CD44 is related to favorable prognosis." (PMID 28910304, 2017). "And we found that CD133, CD44 and Nanog mRNA expressed at a significant higher level in ovarian cancer cell lines SKOV3 and HO8910 exposed for 12 and 24 hours to 1% O2 than that in normoxia (20% O2)." (PMID 28878214, 2017). "First identified in the hematopoietic system, CSCs have been successively identified in many different types of tumors (including ovarian cancer), by several putative markers, such as CD44, CD24, EpCAM, CD133, CD117, ALDH1." (PMID 29187221, 2017). "Combining scFvFITC:sFasL with bortezomib significantly enhanced apoptosis in 3 out 3 primary ovarian cancer samples when pretargeted with anti-CD44-FITC." (PMID 29038485, 2017). "As an example, the expression level of CD44 (one ovarian cancer stem cell marker) was increased in NID1-overexpressed OVCAR-3 cells but decreased in NID1-depleted HEY cells." (PMID 28416770, 2017). "The cells after hyaluronan stimulation throughout CD44 produce TGFbeta and bFGF and in ovarian cancer model CD44 interacts with Her2 and ErbB2 in presence of hyaluronan inducing cell growth." (PMID 29023465, 2017). "In a more clinically-relevant setting, short-term cultures of primary patient-derived ovarian cancer (OC) cells were pretargeted with anti-CD44-FITC, upon which treatment with scFvFITC:sTRAIL induced apoptosis in 6 out of 7 treated samples." (PMID 29038485, 2017). "In vitro TRX-E-002-1 has potent cytotoxic activity against human cancer cells including CD44+/MyD88+ ovarian cancer stem cells." (PMID 28013349, 2017). "TRX-E-002-1 is able to induce cell death in chemo-resistant CD44+/MyD88+ OCSC clones and chemo-sensitive CD44−/MyD88− ovarian cancer cell lines when grown separately or in co-cultures which mimic tumour heterogeneity." (PMID 28013349, 2017). "Our results show that human ovarian cancer ascites cells significantly expressed more CD44-FITC (p < 0.005) and CD133-PE (p < 0.05), compared with primary ovarian tumors." (PMID 27655682, 2016). "In order for metastasis to occur, ovarian cancer cells often alter expression of proteins involved in extracellular matrix interaction, such as CD44, to modulate invasion." (PMID 27253518, 2016). "Restoration of miR-199a-5p expression in ovarian cancer cells has been shown to increase sensitivity to cisplatin, both through targeting mTOR and by targeting CD44, thereby reducing ovarian cancer stem cell levels." (PMID 26717044, 2016). "The lymphocyte homing receptor CD44 was proposed as an ovarian cancer stem cell marker but is also expressed on normal somatic cells (i.e. fibroblasts and reactive mesothelial cells)." (PMID 27665539, 2016). "Similar findings have also been demonstrated in ovarian cancer, non-small-cell lung cancer, and soft tissue sarcomas although high expression of CD44 is also correlated with increased risks of recurrence." (PMID 27148537, 2016). "These ovarian cancer stem-like cells, SKOV3.PX1_133+44+ cells and OVCAR3.PX1_133+44+ cells, behave similarly to the CD133 and CD44 double-positive ascites cells (Ascites_133+44+ cells), which manifested in late-stage ovarian cancers." (PMID 27655682, 2016). "Using flow cytometry, we evaluated CD133 and CD44 expression in human primary-ovarian-cancer specimens (ascites cells, metastatic tumors, ovarian tumors, and normal ovary)." (PMID 27655682, 2016). "CD44 in its standard form located on the surface of ovarian cancer cells contributes to peritoneal metastasis by binding to the hyaluronan coat on mesothelial cells." (PMID 27590006, 2016). "In the literature, CD44 and CD133 expressions were risk factors for ovarian cancer metastasis and poor survival." (PMID 27655682, 2016).
ovarian carcinoma (continued). "CD133 and CD44 expression, alone or together, was the highest in human primary-ovarian-cancer ascites cells." (PMID 27655682, 2016). "In a study of colorectal cancer, the standard isoform CD44s seemed to be correlated with EMT, but higher CD44 expression predicted poor survival in that study in contrast to our results in ovarian cancer." (PMID 27590006, 2016). "Activation of another tyrosine kinase, c-Src, by the CD44–HA complex stimulates a rearrangement of cytoskeleton proteins and increases migration in breast and ovarian cancers." (PMID 25129125, 2015). "The results showed that surgical stage, CD44 expression, CD47 expression and c-met expression were independent risk factors for ovarian cancer prognosis." (PMID 25658794, 2015). "The aim of this study is to evaluate the clinical significance of CD44 expression by using a unique tissue microarray, and then to determine the biological functions of CD44 in ovarian cancer." (PMID 25823654, 2015). "Our study demonstrated that both the metastatic and recurrent ovarian cancer tissues expressed higher levels of CD44 than patient-matched primary tumor samples." (PMID 25823654, 2015). "In conclusion, we demonstrate CD44 is significantly up-regulated during the progression of human ovarian cancer, including recurrence, metastasis, and acquisition of drug resistance." (PMID 25823654, 2015). "These markers are numerous and differ depending on the tissue origin, however for ovarian cancer, one of the most reported examples is increased CD44 expression." (PMID 25886038, 2015). "We first determined the expression level of CD44 in ovarian cancer drug sensitive and resistant cell lines SKOV-3 and SKOV-3TR." (PMID 25687880, 2015). "For quite some time, the role of CD44 in ovarian cancer progression and metastasis has remained unclear." (PMID 26569327, 2015). "From these results, we concluded that the SKOV3 ovarian cancer growth was significantly inhibited in the mice vaccinated with the SKOV3 CD117+CD44+CSC-based vaccine." (PMID 26497895, 2015). "The connection between JAK2/STAT3 pathway activation and CSCs has been highlighted in a previous work on ovarian cancer, where the SC marker CD44 together with the embryonic SC marker NANOG have been associated with the activation of STAT3." (PMID 26312765, 2015). "The clinical significance of Cluster of Differentiation 44 (CD44) remains controversial in human ovarian cancer." (PMID 25823654, 2015). "Our findings suggest that CD44 targeted HA-PEI/HA-PEG/MDR1 siRNA nanoparticles can serve as a therapeutic tool with great potentials to circumvent MDR in ovarian cancer." (PMID 25687880, 2015). "Although miR-199a was reported to target CD44 in ovarian cancer, additional studies are needed to further characterize these CD44 regulatory mechanisms in epithelial ovarian cancer." (PMID 26569327, 2015). "Versican treatment can induce ovarian cancer cell invasion through an ECM barrier, and suggest that formation of a CD44/hyaluronan/versican macromolecular complex promotes the motility and invasion of ovarian cancer cells." (PMID 26515726, 2015). "Our results indicated that expression of CD47 was comparable to expression of CD44 in different ovarian cancer subtypes and displayed a positive correlation." (PMID 25658794, 2015). "Both the metastatic and recurrent ovarian cancer tissues expressed higher levels of CD44 than the primary tumor." (PMID 27600234, 2015). "The aim of this study is to further investigate and clarify expression and function of CD44 in ovarian cancer." (PMID 25823654, 2015). "In a previous study, we treated an ovarian cancer mouse xenograft with siRNA targeting CD44, and showed that the resulting reduction of CD44 expression in the tumor correlated with decreased expression of P-gp and increased drug cytotoxicity." (PMID 26299618, 2015).
ovarian carcinoma (continued). "In order to more strategically design therapeutics for ovarian cancer, it is crucial to not only identify, but fully characterize targets, like CD44, which play a role in recurrence, metastasis, and drug resistance in ovarian cancer." (PMID 26569327, 2015). "Although the effects of CD44 inhibition in cancer therapy remain controversial, numerous reports have shown effective reduction of malignancies, including colon, mammary, and ovarian cancers, following treatment with CD44 inhibitors." (PMID 25331984, 2015). "A few studies have investigated the role of CD44 glycosylation and HA adhesion in ovarian carcinoma cells." (PMID 26569327, 2015). "Both the metastatic and recurrent ovarian cancer tissues expressed higher level of CD44 than the patient-matched primary tumor." (PMID 25823654, 2015). "The CD117+ CD44+CSC vaccine increased anti-ovarian cancer efficacy in that it depressed ovarian cancer growth in the athymic nude mice." (PMID 26497895, 2015). "Based on current understanding, CD44 remains promising as a therapeutic target in ovarian cancer and, thus, warrants further evaluation." (PMID 26569327, 2015). "Recently, it was shown that Lewis y antigen, as a structure within the CD44 molecule, strengthens CD44-mediated adhesion to HA and the spreading of ovarian cancer cells." (PMID 26569327, 2015). "Results from drug sensitive and resistant cell lines and from xenograft mouse model of ovarian cancer indicated that up-regulation of CD44 is a critical event during the progression of ovarian cancer." (PMID 25823654, 2015). "CD117+CD44+CSCs were isolated from human epithelial ovarian cancer (EOC) SKOV3 cell line by using a magnetic-activated cell sorting system." (PMID 26497895, 2015). "In the current study, we provided a comprehensive overall expression profile of CD44 in ovarian cancer, from individual patients’ clinical primary tumor tissue to metastasis and recurrence, and from tumor cell lines to xenograft mouse model." (PMID 25823654, 2015). "This further supports a role for CD44 together with HA and versican in a number of key steps needed for ovarian cancer metastasis." (PMID 26569327, 2015). "Despite CD44 is frequently expressed in a wide variety of epithelial malignancies, including ovarian cancer." (PMID 25823654, 2015). "This review highlights recent advances in our understanding of the role CD44 plays in the biology of ovarian cancer." (PMID 26569327, 2015). "When CD44 was stably inhibited by its specific shRNA, the proliferation speed and spheroids formation of ovarian cancer cells was inhibited under 3-D culture conditions." (PMID 25823654, 2015). "In order to investigate the biology of CD44 in ovarian cancer, we stably transduced ovarian cancer OVCAR8 cells by a lentivirus-mediated gene transfer system expressing CD44 shRNA." (PMID 25823654, 2015). "Downregulation of CD44 by miR-199a-3p significantly increased the chemosensitivity of ovarian cancer cells to cisplatin, pacitaxel, and adriamycin." (PMID 25823654, 2015). "Further investigation into the cross-talk between CD44 and inflammatory signaling in ovarian cancer will hopefully lead to a better understanding of more effective focal points for therapeutic intervention." (PMID 26569327, 2015). "Denatured platelets are incapable elevating CD44 and N-Cadherin, or decreasing E-Cadherin protein levels in ovarian cancer cells." (PMID 25886038, 2015). "In accordance with a former study, down-regulation of CD44 by miR-199a-3p remarkably increased the chemosensitivity to cisplatin, paclitaxel, and adriamycin in ovarian cancer cells." (PMID 26079799, 2015). "Previous reports have found that suppressing CD44 by its specific siRNA dramatically decreases the migratory potentials and invasiveness of ovarian cancer cells." (PMID 25823654, 2015). "CD44 is frequently expressed in a wide variety of epithelial malignancies, including ovarian cancer." (PMID 26569327, 2015).
ovarian carcinoma (continued). "We have similar findings when knocking down CD44 by efficient and specific esiRNA in malignant drug resistant ovarian cancer cell lines." (PMID 25823654, 2015). "In an effort to develop new and effective treatment strategies for advanced-stage ovarian cancer patients, CD44 is also being explored as a therapeutic target." (PMID 26569327, 2015). "As an example, HA from mesothelial cells, the major cell population in the peritoneum, is an adhesion factor for CD44-positive ovarian cancer cells." (PMID 24739440, 2014). "In fact, CD44 shedding has been observed in many human tumors, including breast, lung, colon and ovarian carcinomas, and indeed takes part in tumorigenesis and tumor metastasis." (PMID 24410905, 2014). "CD44 is expressed in ovarian cancers and binds hyaluronic acid (HA), a glycosaminoglycan that is synthesized by mesothelial cells." (PMID 24567915, 2014). "TICs have been identified in both human and murine ovarian cancers by sorting for CD44, CD133, CD117, CD24, ALDH1, and SCA1 expression alone or in combination." (PMID 24672774, 2014). "Although CD133 and CD44 are thought to be indicative of CSCs in some types of cancer, it remains to be elucidated what markers are appropriate for CSCs in ovarian cancers." (PMID 25375122, 2014). "We show that in contrast to the more differentiated ovarian cancer cells, the putative CD44+/MyD88+ ovarian cancer stem cells express lower levels of pyruvate dehydrogenase, Cox–I, Cox-II, and Cox–IV, and higher levels of UCP2." (PMID 25237928, 2014). "Both endogenous c-kit and CD44 are expressed in ovarian cancer cells and ovarian cancer tissues of patients and mice, and to be candidate cell surface markers for ovarian tumor progenitors." (PMID 24721839, 2014). "Hyaluronic acid bioconjugates with paclitaxel are being studied to enhance selective entry of cytotoxic drugs into human EOC cells expressing CD44 and for its use in intraperitoneal treatment of ovarian carcinoma." (PMID 23902592, 2013). "Several studies have revealed that CD44s is highly expressed in situ and metastatic ovarian cancers and that CD44 expression is correlated with malignant behaviors of ovarian cancer cells, such as adhesion, invasion, and metastasis." (PMID 23468946, 2013). "Ovarian cancer tumors are heterogeneous and in our previous reports we have shown that both subtypes of cells (CD44+/MyD88+ and CD44−/MyD88−) are present in the tumors." (PMID 24403249, 2013). "TNF-α has been reported to increase CD44 expression on ovarian cancer cells upon the activation of the c-Jun NH2-terminal kinase and, although not in the context of cancer, affects the glycosylation and sulfation of various glycoproteins." (PMID 23372803, 2013). "Our results show that HA induces chemoresistance against CBP, and increases the expression of the ABC transporters, ABCB3, ABCC1, ABCC2, and ABCC3 in ovarian cancer cell lines expressing the HA receptor, CD44." (PMID 24124770, 2013). "The CD44+CD117+cells isolated from human epithelial ovarian cancer SKOV-3 cell line using magnetic-activated cell sorting were found to grow faster than the SKOV-3 cells in the 3D culture and in the nude mice." (PMID 23368632, 2013). "Our findings confirm that, in addition to their important role in promoting malignant ovarian cancer cell behaviour, CD44-HA interactions also play a significant role in mediating chemoresistance." (PMID 24124770, 2013). "In ovarian cancer, CD44+CD117+ cells were identified as a subpopulation of cells from the primary tumor, with sustained capacity to initiate tumorigenesis in xenografts, in contrast to CD44-CD117- cells." (PMID 23528888, 2013). "As expected, most ovarian cancer cell lines showed an increase in the CD44+CD117+ subpopulation after FSH treatment." (PMID 23921511, 2013). "Two other studies have independently defined ovarian cancer SC by evaluating CD44+ CD117+ and CD133+ phenotypes." (PMID 23902592, 2013).